DMD (dystrophin)
Diseases named in the same sentence as DMD in open-access papers (continued):
Sharing a sentence is not in itself a finding about the gene and the disease.
Duchenne muscular dystrophy (continued). "Duchenne muscular dystrophy (DMD) is a lethal disease caused by deletions in one or more exons of the dystrophin gene (mainly exons 45, 48 and 51) causing a reading frameshift and premature termination, resulting in a truncated dysfunctional protein and consequently muscle degeneration." (PMID 36963162, 2023). "One of the first reports in 2014 described a zebrafish model of Duchenne muscular dystrophy (DMD), a muscle-degenerative disease caused by mutations in the dystrophin gene, which is also expressed in the zebrafish skeletal muscle." (PMID 37446400, 2023). "We previously developed the dissociative corticosteroid vamorolone for treatment of the allelic, dystrophin-null disease Duchenne muscular dystrophy." (PMID 37534133, 2023). "The expression of dystrophin, the missing or defective protein in Duchenne muscular dystrophy, is not limited to muscle cells but also extends to vascular endothelial cells." (PMID 38274452, 2023). "Duchenne muscular dystrophy (DMD), which mostly affects males, is an X chromosome-linked recessive genetic disorder that prevents the synthesis of a functional dystrophin protein." (PMID 37296659, 2023). "For instance, in Duchenne muscular dystrophy (DMD), the mutation in the DMD gene prevents the expression of the dystrophin protein that plays an important role in muscle fiber stability, leading to chronic degeneration, inflammation, and fibrosis." (PMID 36538023, 2023). "The most severe and the most common adult form of MD is Duchenne Muscular Dystrophy (DMD), which affects 1 in 3500–6000 live male births, and is caused by the lack of functional dystrophin protein due to mutations in the dystrophin gene (DMD)." (PMID 36901738, 2023). "Duchenne muscular dystrophy (DMD) is characterised by the absence of dystrophin protein and results in muscle cell fragility, inflammatory change, and the accumulation of fibrotic tissue and fat in skeletal muscles." (PMID 37768006, 2023). "PPARβ agonists (e.g., GW501516) activate PPARβ and provide functional improvements in Duchenne muscular dystrophy (DMD) patients by increasing utrophin A (an autosomal homolog of dystrophin) expression." (PMID 35565236, 2022). "This review highlights the important contribution of abnormal calcium handling and impaired excitation–contraction coupling in Duchenne muscular dystrophy, a neuromuscular disorder that is triggered by the disintegration of the dystrophin‐glycoprotein complex." (PMID 35902360, 2022). "Duplications are the main type of dystrophin gene (DMD) variants, which typically cause dystrophinopathies such as Duchenne muscular dystrophy and Becker muscular dystrophy." (PMID 36360209, 2022). "Duchenne muscular dystrophy is characterized by the absence or decreased expression of dystrophin; to evaluate therapy efficacy, it is necessary to quantify and locate dystrophin in skeletal muscle, but the current methods lack reproducibility and sensitivity." (PMID 35888125, 2022). "PTEN and PI3K/Akt signaling has also been implicated in primary muscle disorders, including Duchenne muscular dystrophy (DMD), caused by mutations in the dystrophin gene." (PMID 35731367, 2022). "In a trial for treatments of Duchenne muscular dystrophy (DMD) injection of an AAV9 vector expressing mini-dystrophin resulted in TMA in 4 out of 15 male recipients between the ages of 7-12 years." (PMID 36032092, 2022). "Duchenne muscular dystrophy (DMD) is an X-linked recessive neuromuscular disease caused by loss of function mutations in DMD, the gene encoding the dystrophin protein." (PMID 35998119, 2022). "Patients with Duchenne muscular dystrophy (DMD) are at particular risk of significant blood loss; patients with DMD are deficient of dystrophin in all muscle types and may have impaired vasoconstrictive responses." (PMID 36554043, 2022). "Duchenne muscular dystrophy (DMD) is a severe, progressive, and incurable X-linked disorder caused by mutations in the dystrophin gene." (PMID 35935842, 2022).
Duchenne muscular dystrophy (continued). "In the first case we have a mutation in genes that affects muscle tissue directly (as in dystrophin in the case of Duchenne muscular dystrophy), which leads to atrophy and death of muscle cells." (PMID 36550950, 2022). "Duchenne muscular dystrophy (DMD) is a genetic disorder characterized by muscle degeneration due to the mutant muscle protein dystrophin." (PMID 36158194, 2022). "We concentrated on the commonly caused premature termination codon (PTC) in dystrophin (DMD) mRNA, causing Duchenne muscular dystrophy." (PMID 35536311, 2022). "For example, Duchenne muscular dystrophy (DMD), a progressive dystrophin mutation-related muscle-wasting disease, increases sarcolemmal membrane fragility and causes muscle damage even under mild stress." (PMID 35216455, 2022). "Duchenne muscular dystrophy (DMD), an X-linked disorder caused by loss-of-function mutations in the dystrophin gene, is characterized by progressive muscle degeneration and weakness." (PMID 35939054, 2022). "Duchenne muscular dystrophy (DMD) is a clinically common X-linked recessive myopathy, which is caused by mutation of the gene encoding dystrophin on chromosome Xp21." (PMID 35987773, 2022). "Duchenne muscular dystrophy is an example of genotype/phenotype correlations; and the DMD gene contains a number of partially dispensable exons, as we and others have observed some functional protein is preferable to no functional protein." (PMID 35392567, 2022). "High expectations have been set on gene therapy with an AAV-delivered shortened version of dystrophin (μDys) for Duchenne muscular dystrophy (DMD), with several drug candidates currently undergoing clinical trials." (PMID 35039573, 2022). "Duchenne muscular dystrophy (DMD) is an X-linked genetic disease due to a mutation of DMD gene, which encodes DYSTROPHIN." (PMID 35377913, 2022). "After confirming the Becker-form dystrophin protein that has X chromosome-linked mutation in cell culture in vitro, AAV1 vectors were transferred into the muscle of Duchenne muscular dystrophy mouse model, resulting in therapeutic gene expression and benefits." (PMID 35211511, 2022). "Duchenne muscular dystrophy (DMD) is caused by mutations in the X-linked dystrophin gene." (PMID 35401829, 2022). "In Duchenne muscular dystrophy, due to dystrophin absence, the distribution of endplate acetylcholine receptors (AChRs) becomes disorganized." (PMID 36430996, 2022). "Interestingly, pathogenic variants in the dystrophin (DMD) gene, responsible for Duchenne muscular dystrophy (DMD) and its allelic and less severe form Becker muscular dystrophy (BMD) have been recognized as risk variants for ASD." (PMID 37861890, 2022). "This is due to the very active research on Duchenne muscular dystrophy and in particular on the development of exon-skipping strategies to restore dystrophin function." (PMID 35213992, 2022). "Duchenne muscular dystrophy (DMD) and Becker muscular dystrophy (BMD) are neuromuscular recessive disorders due to the X-linked mutation in the dystrophin gene." (PMID 36419457, 2022). "Muscle fibrosis is a structural hallmark of Duchenne muscular dystrophy (DMD), an X-linked degenerative genetic illness caused by mutations of the DMD gene encoding the dystrophin protein." (PMID 35955872, 2022). "For example, in the case of the Duchenne muscular dystrophy, ASO-mediated manipulation of pre-messenger RNA splicing bypass the Duchenne-causing mutations in DMD (dystrophin) and restore functional expression of the DMD protein." (PMID 35585060, 2022). "Viltolarsen demonstrated in a phase 1/2 study that intravenous infusions of 80 mg/kg/week for 24 weeks in Japanese Duchenne muscular dystrophy patients increased mean dystrophin levels by 2.8% by Western blot analysis." (PMID 35886024, 2022). "Duchenne muscular dystrophy (DMD) is the most common hereditary disease among progressive muscular dystrophy and is caused by a dystrophin gene mutation." (PMID 36135023, 2022).
Duchenne muscular dystrophy (continued). "Duchenne muscular dystrophy (DMD) is a fatal, X-linked genetic condition caused by dystrophin deficiency in striated muscle that affects ∼1 in 5000 male births." (PMID 35019137, 2022). "Duchenne Muscular Dystrophy (DMD) is a fatal, X-linked disease, due to nonsense mutations in the dystrophin gene." (PMID 35455028, 2022). "Duchenne muscular dystrophy (DMD) is a progressive, X-linked childhood neuromuscular disorder that results from loss-of-function mutations in the DYSTROPHIN gene." (PMID 36289662, 2022). "For example, in Duchenne muscular dystrophy (DMD), exon skipping is utilized to reestablish the correct reading frame where a mutated exon that contains a frameshift is skipped to restore production of a partially functional dystrophin protein." (PMID 35054974, 2022). "We examined four more loci, including Duchenne muscular dystrophy (DMD) exon 53 and DMD exon 44 (537 kb away from each other), the 5′ coding region of HBB and an intergenic locus intragenic 1 (GRCh38.p13, chromosome 20, 32752960–32752979)." (PMID 35323942, 2022). "Duchenne muscular dystrophy (DMD) is a fatal disease caused by mutations in the dystrophin gene." (PMID 36498987, 2022). "Duchenne muscular dystrophy (DMD) represents one of the most common, severe, and lethal types of dystrophinopathies, which are caused by mutations in the X-linked DMD gene that encodes dystrophin, a structural muscle protein." (PMID 36441348, 2022). "Utrophin-A acts as a promising surrogate for missing dystrophin proteins in the muscles of patients with Duchenne muscular dystrophy (DMD)." (PMID 35628242, 2022). "Duchenne muscular dystrophy (DMD) is an X-linked recessive myopathy caused by dystrophin mutations." (PMID 35803994, 2022). "In Duchenne muscular dystrophy (DMD), these problems have been linked to mutations along the dystrophin gene affecting different brain dystrophin isoforms." (PMID 36215287, 2022). "Duchenne muscular dystrophy (DMD) and Becker muscular dystrophy (BMD) are X-linked recessive hereditary diseases caused by mutations in the DMD gene (OMIM∗300377)." (PMID 33936175, 2021). "Duchenne muscular dystrophy (DMD) is an X-linked genetic disease affecting ∼1:3500 to 1:5000 males worldwide, caused by loss of dystrophin expression." (PMID 33869226, 2021). "Next, we selected MaxCyte condition E8 to examine the efficiency of ssODN-mediated knockin into Duchenne muscular dystrophy patient iPSCs (CiRA00111) with exon 44 deletion in the DMD gene." (PMID 33711268, 2021). "The dystrophinopathies, Duchenne muscular dystrophy (DMD) and allelic Becker muscular dystrophy (BMD), are X-linked recessive disorders caused by mutations in the DMD gene that result in deficient dystrophin production." (PMID 34682100, 2021). "Duchenne muscular dystrophy (DMD), an X-linked recessive neuromuscular disease with an incidence of 1 in 3600–6000 boys, is caused by loss-of-function mutations or deletions in gene encoding dystrophin." (PMID 34012406, 2021). "In contrast, frameshifting mutations are mainly associated with severe Duchenne muscular dystrophy (DMD OMIM 310200) and cause a complete absence or severe reduction of the dystrophin protein." (PMID 34305639, 2021). "Lastly, viral gene transfer of full-length genes has been used to restore function of wild type proteins (e.g., dystrophin protein for treatment of Duchenne Muscular Dystrophy)." (PMID 34276779, 2021). "Genetic mutation analysis using multiplex ligation-dependent probe amplification method revealed hemizygous deletion encompassing final 35 exons (exon 45 to 79) of the dystrophin gene confirming the diagnosis of Duchenne muscular dystrophy." (PMID 34689766, 2021). "Duchenne muscular dystrophy (DMD), caused by mutations in the dystrophin gene, is an inherited neuromuscular disorder that causes loss of muscle mass and motor skills." (PMID 33808773, 2021).
Duchenne muscular dystrophy (continued). "Emerging and promising therapeutic interventions for Duchenne muscular dystrophy (DMD) are confounded by the challenges of quantifying dystrophin." (PMID 33441839, 2021). "Duchenne muscular dystrophy (DMD), an X-linked muscle degenerative disorder caused by deficient or defective synthesis of dystrophin protein, is the most common inherited muscular dystrophy and affects both skeletal muscle and myocardial muscle." (PMID 34645467, 2021). "Duchenne muscular dystrophy (DMD) is a progressive, X-linked neuromuscular disorder caused by mutations in the dystrophin-encoding DMD gene." (PMID 34420127, 2021). "Duchenne muscular dystrophy (DMD) is a fatal, progressive muscle disease caused by the absence of functional dystrophin protein." (PMID 34305644, 2021). "In the last few years, the development of new outcome measures has allowed a better definition of the natural history of Duchenne Muscular Dystrophy (DMD), a progressive, X-linked neuromuscular disorder caused by mutation in the dystrophin gene, affecting one in 3600–5000 live male births." (PMID 34833484, 2021). "Duchenne muscular dystrophy (DMD), one of the most common progressive and severely disabling neuromuscular diseases in children, can be largely attributed to the loss of function of the DMD gene on chromosome Xp21.2-p21.1." (PMID 34899847, 2021). "ΔR4-R23/ΔCT micro-dystrophin (μDys) is a miniaturized version of dystrophin currently evaluated in a Duchenne muscular dystrophy (DMD) gene therapy trial to treat skeletal and cardiac muscle disease." (PMID 33949649, 2021). "For example, gold nanoparticles complexed with donor DNA, Cas9 RNP, and the endosomal disruptive polymer PAsp(DET) rescued dystrophin expression and the muscle phenotype when delivered in vivo to a mouse model of Duchenne muscular dystrophy." (PMID 34713254, 2021). "In this paper, we report a clinical case of a patient affected by ASD and Duchenne muscular dystrophy, who carries a large deletion of the dystrophin gene." (PMID 34640386, 2021). "Here, the authors show that local and systemic AAV CRISPR therapy induces cytotoxic killing and eliminates rescued dystrophin in canine models of Duchenne muscular dystrophy." (PMID 34819506, 2021). "Duchenne muscular dystrophy (DMD), caused by the loss of dystrophin, remains incurable." (PMID 34680151, 2021). "Genetic analysis revealed hemizygous deletion involving the final 35 exons of the dystrophin gene confirming the diagnosis of Duchenne muscular dystrophy." (PMID 34689766, 2021). "One of these pathologies is Duchenne muscular dystrophy (DMD), caused by mutations in the gene encoding the dystrophin protein in muscles." (PMID 34575944, 2021). "The systematic bioanalytical characterization of the protein product of the DMD gene, which is defective in the pediatric disorder Duchenne muscular dystrophy, led to the discovery of the membrane cytoskeletal protein dystrophin." (PMID 33540575, 2021). "A third condition for which vibration may be applied is for Duchenne muscular dystrophy (DMD), which is a degenerative disorder caused by a defective gene responsible for producing a muscular protein called dystrophin." (PMID 34069792, 2021). "Transplantation of skeletal muscle came into play in the early 1990s and aimed to restore dystrophin production in patients with Duchenne muscular dystrophy (DMD)." (PMID 33349909, 2021). "Duchenne muscular dystrophy (DMD) is a hereditary disease, genetically recessive, formed by a mutation of the dystrophin gene and positioned on the Xp21 chromosome." (PMID 34440496, 2021). "The DE50-MD dog, a recently established canine model of Duchenne muscular dystrophy (DMD), has a point mutation in the 5’ donor splice site of intron 50 that results in deletion of exon 50 from dystrophin gene transcripts, with concomitant frameshift and premature protein truncation." (PMID 35600245, 2021).
Duchenne muscular dystrophy (continued). "Duchenne muscular dystrophy (DMD) is the most common, progressive, irreversible muscular dystrophy, caused by mutations in the X-linked dystrophin gene." (PMID 34501557, 2021). "The results indicated that the patients with a mutation in the dystrophin isoform Dp116 are prone to cardiac dysfunction, thus leading to the conclusion that suppressing this dystrophin isoform may hinder cardiac dysfunction in Duchenne muscular dystrophies patients." (PMID 34066119, 2021). "Duchenne muscular dystrophy (DMD) is an X-linked genetic disorder and the most common form of muscular dystrophy caused by mutations in the dystrophin gene that lead to essential shortage of the functional protein." (PMID 34367346, 2021). "One hundred and seventeen different deletions and 48 duplications in the DMD gene were found in 507 Korean patients with Duchenne muscular dystrophy or Becker muscular dystrophy." (PMID 33430289, 2021). "Outside the context of Duchenne muscular dystrophy, evidence for the involvement of the DMD gene in STS development is growing." (PMID 33188621, 2021). "After the addition of AP21967, EVs were isolated and added to recipient HEK293T cells expressing a specific sgRNA targeting DMD1 (the SA site of exon 45 in the human dystrophin gene that is mutated in DMD, Duchenne muscular dystrophy)." (PMID 34199901, 2021). "In a phase I/II clinical trial, six Duchenne muscular dystrophy patients received the mini-dystrophin transgene intramuscularly." (PMID 34777364, 2021). "Duchenne Muscular Dystrophy (DMD) and Becker Muscular Dystrophy (BMD) are X-linked recessive neuromuscular disorders due to mutations in the dystrophin gene (MIM 300377)." (PMID 33494189, 2021). "In vivo editing studies have been explored in genetic muscular diseases, for example, Duchenne muscular dystrophy (DMD), characterized by progressive muscle weakness and premature death due to mutation in the dystrophin gene." (PMID 33750221, 2021). "For instance, this approach has been of high utility in Duchenne muscular dystrophy, where AONs can efficiently restore the reading frame of the dystrophin gene by blocking splice sites and bypassing the target exons." (PMID 33924840, 2021). "Considerable emphasis has been placed on Duchenne Muscular Dystrophy (DMD), which is the most common genetic form of the muscular dystrophies, occurring at a frequency of about 1 in 5,000 boys due to loss of function mutations in the dystrophin gene (DMD) on the X chromosome." (PMID 33770101, 2021). "Flanigan and colleagues report the results of an intravenous dose-escalation study using an AAV9-encapsidated U7snRNA vector to skip DMD exon 2 and restore dystrophin expression in the Dup2 mouse model of Duchenne muscular dystrophy." (PMID 33898631, 2021). "Duchenne muscular dystrophy (DMD) is the most common muscular dystrophy and is characterized by a loss of the dystrophin protein leading to inflammation, cell infiltration, fibrosis, and necrosis of skeletal muscle." (PMID 33806433, 2021). "Another example is Duchenne muscular dystrophy (DMD) disease that is marked by DMD gene mutation at locus Xp21, causing a decrease in dystrophin protein production and subsequently, impaired muscular integrity." (PMID 34446084, 2021). "Duchenne muscular dystrophy (DMD) is a lethal, X-linked neuromuscular disorder caused by the absence of dystrophin protein, which is essential for muscle fiber integrity." (PMID 34490244, 2021). "In Duchenne muscular dystrophy (DMD) patients, ASO‐induced exon skipping of mutated dystrophin pre‐mRNA restores the reading frame and allows for the production of partially functional, rather than non‐functional, dystrophin protein." (PMID 33821570, 2021). "Duchenne muscular dystrophy (DMD) is a severe muscle-wasting disease caused by frameshift or nonsense mutations in the DMD gene, resulting in the loss of dystrophin from muscle membranes." (PMID 33567244, 2021).